OSM (oncostatin M)
Diseases named in the same sentence as OSM in open-access papers (continued):
Sharing a sentence is not in itself a finding about the gene and the disease.
viral infection (4 papers, 2015 to 2024). "DEGs unique to infected cells mapped to host defense (MYD88, C3, CASP4, JAK2, and OSM), viral infection (RNASE6 and SVVORFs), and protein synthesis (RPL18 and RPS16)." (PMID 38887303, 2024). "OSM upregulation was a specific feature of NAFLD/NASH‐derived HCC, since OSM serum levels were higher than those detected in patients with HCCs of non‐NAFLD etiologies, e.g. associated with viral infection or alcohol use disorder." (PMID 35064579, 2022). "Their findings suggested that OSM could be expressed by both ciliated and goblet cells, disrupting the tight junctions following viral infections, and possibly exposing the subepithelia to invading pathogens to elicit inflammatory responses, causing exacerbations in CRSwNP." (PMID 38116043, 2023). "In addition, it has been demonstrated that inflammatory cytokines, such as oncostatin M (OSM), hepatocyte growth factor (HGF), interferon-γ (IFN-γ), and toll-like receptors 7 and 8 (TLR7/8), when stimulated by viral infections, can trigger KSHV reactivation." (PMID 25594835, 2015).
chondrosarcoma (3 papers, 2005 to 2022). A malignant cartilaginous matrix-producing mesenchymal neoplasm arising from the bone and soft tissue. "OSM inhibits cell proliferation via the JAK/STAT pathway in a number of tumor cells, including OS and chondrosarcoma." (PMID 23213280, 2012).
diabetes (3 papers, 2023 to 2026). "Our results also revealed that another five proteins (HGF, CD6, fibroblast growth factor 21 (FGF-21), LIF-R, and OSM) might mediate the associations of gut bacteria with diabetes." (PMID 38643166, 2024).
Kaposi's sarcoma (3 papers, 2011 to 2022). A malignant neoplasm characterized by a vascular proliferation which usually contains blunt endothelial cells. "Dependence on cytokines, such as basic fibroblast growth factor, oncostatin M and interleukin 6, has been shown for the growth of Kaposi’s sarcoma-derived cells in vitro." (PMID 35267506, 2022). "Third, corticosteroid stimulation of KS development can also occur through upregulation of oncostatin M and IL-6/sIL-6R and blockade of transforming growth factor-β, an autocrine inhibitory factor for Kaposi's sarcoma." (PMID 28736762, 2017).
leukemia (3 papers, 2015 to 2025). A malignant (clonal) hematologic disorder, involving hematopoietic stem cells and characterized by the presence of primitive or atypical myeloid or lymphoid cells in the bone marrow and the blood. "OSM, as a cytokine fulfilling several functions, is most closely associated with leukemia inhibitory factors." (PMID 39683503, 2024).
multiple sclerosis (3 papers, 2011 to 2025). A progressive autoimmune disorder affecting the central nervous system resulting in demyelination. "OSM is a member of the IL-6 cytokine family and has previously been shown to play a neuroprotective role in spinal cord injury and multiple sclerosis (MS)." (PMID 41562085, 2025). "Upregulation of OSM is found in multiple sclerosis lesions in the brain in microglia, reactive astrocytes, infiltrating leukocytes, as well as in peripheral blood mononuclear cells." (PMID 21479182, 2011).
osteosarcoma (3 papers, 2019 to 2022). A usually aggressive malignant bone-forming mesenchymal neoplasm, predominantly affecting adolescents and young adults.
prostate carcinoma (3 papers, 2016 to 2024). A carcinoma that arises from epithelial cells of the prostate gland. "Patients with prostate cancer exhibited increased serum oncostatin-M, but no changes occurred in other myokines; exercise-conditioned serum from these patients inhibited the growth of prostate cancer cells." (PMID 38928185, 2024). "Finally, the Interleukin-6 family member, Oncostatin M (OSM), has previously been shown to promote proliferation and survival in prostate cancer cells." (PMID 27036029, 2016).
Pruritus (3 papers, 2024 to 2025). Pruritus is an itch or a sensation that makes a person want to scratch. "Recent data implicate Th2‐associated cytokines such as interleukin‐4 (IL‐4), IL‐13, IL‐31 and oncostatin M (OSM) as important mediators of pruritus and responsible for PN typical epidermal hyperplasia, inflammation and fibrosis." (PMID 40600744, 2025). "Our research suggests that targeting OSM as a therapeutic approach may be effective for pruritus that is refractory to treatment, such as alloknesis." (PMID 40677708, 2025). "These OSM functions may be involved in the pathogenesis of CPG and contribute to its association with pruritus." (PMID 38493053, 2024).
pulmonary disease (3 papers, 2019 to 2022). "The OSM/OSM receptor pathways are indeed intriguing, and further exploration will generate potentially new approaches in treating chronic inflammation, including that found in pulmonary disease." (PMID 31817403, 2019). "Oncostatin M (OSM) plays a role in various inflammatory reactions, and neutrophils are the main source of OSM in pulmonary diseases." (PMID 35011361, 2021).
renal fibrosis (3 papers, 2017 to 2020). A final common manifestation of a wide variety of chronic kidney diseases characterized by glomerulosclerosis and tubulointerstitial fibrosis. "Taking into account the dual role of OSM in renal fibrosis, we first detected the level of OSM in the renal cortex by ELISA." (PMID 28626343, 2017). "OSM signaling thus promotes renal fibrosis in the process of kidney stone formation." (PMID 33051515, 2020). "Moreover, treatment with anti-OSM antibody ameliorated renal fibrosis in obstructive nephropathy." (PMID 28626343, 2017). "We have shown that anti-OSM antibody increased the expression of E-cadherin and decreased the expression of α-SMA, suppressed the expression of MCP-1 and ICAM-1, attenuated renal fibrosis, and partially improved 24-hour urinary protein excretion and BUN production." (PMID 28626343, 2017). "Another recent study investigating the effects of an anti-OSM antibody in a murine model of lupus nephritis demonstrated that OSM-driven EMT and extracellular matrix secretion, leading to renal fibrosis, could be suppressed, concomitant with the suppression of JAK/STAT3 activation." (PMID 31684144, 2019).
retinal degeneration (3 papers, 2011 to 2020). Degeneration of the retina. "Recombinant OSM, protected both rod and cone photoreceptors from degeneration in a transgenic rat model of retinal degeneration." (PMID 28575111, 2017). "In our experiments, we used recombinant human OSM on rat model of retinal degeneration." (PMID 21479182, 2011).
Thrombocytopenia (3 papers, 2024 to 2025). A reduction in the number of circulating thrombocytes. "Interestingly, sgp130Fc has a reassuring safety profile, including the absence of platelet toxicity, even when used at concentrations expected to inhibit OSM signalling, which is intriguing considering that direct targeting of OSM causes thrombocytopenia." (PMID 38338642, 2024).
triple-negative breast carcinoma (3 papers, 2019 to 2024). An invasive breast carcinoma which is negative for expression of estrogen receptor (ER), progesterone receptor (PR), and human epidermal growth factor receptor 2 (HER2). "For instance, in the wake of chemotherapy, macrophages have been known to secrete oncostatin M (OSM), a cytokine from the IL-6 family, propelling the dedifferentiation of aggressive stem cells into triple-negative breast cancer cells." (PMID 38329598, 2024). "OSM-mediated signaling has also been shown to contribute to the growth and invasion of triple-negative breast cancer." (PMID 35565185, 2022).
allergic disease (2 papers, 2020 to 2025). An immune response that occurs following re-exposure to an innocuous antigen, and that requires the presence of existing antibodies against that antigen. "Oncostatin M (OSM), a potent pro-inflammatory cytokine associated with various cutaneous inflammatory and allergic diseases, was downregulated (-6.7 fold)." (PMID 32886659, 2020). "For oncostatin-M (OSM), cystatin D (CST5) and hepatocyte growth factor (HGF) similar changes between visits were observed in both allergy groups." (PMID 40929127, 2025).
Alzheimer disease (2 papers, 2016 to 2018). A progressive, neurodegenerative disease characterized by loss of function and death of nerve cells in several areas of the brain leading to loss of cognitive function such as memory and language. "Elevated levels of oncostatin M (OSM), an interleukin-6 cytokine family member, have been observed in HIV-1-associated neurocognitive disorders (HAND) and Alzheimer’s disease." (PMID 27287400, 2016).
Autoimmunity (2 papers, 2024). The occurrence of an immune reaction against the organism's own cells or tissues. "The OSM and LIF genes, members of the IL-6-related family, are pleiotropic cytokines with similar genetic structures and physiological functions that play important roles in chronic inflammation, autoimmunity, infectious diseases, and cancer." (PMID 38591204, 2024).
bladder cancer (2 papers, 2017 to 2023). "In addition, discrete groups of tumor cells were found to be associated with oncostatin M signaling, bladder cancer signaling, and paxillin signaling." (PMID 28977854, 2017).
breast invasive ductal carcinoma (2 papers, 2022). "In invasive ductal carcinoma (IDC) tissues, patients with high LOXL2 and oncostatin M (OSM) co-expression are more prone to metastasis." (PMID 36293126, 2022).
Cachexia (2 papers, 2015 to 2025). Severe weight loss, wasting of muscle, loss of appetite, and general debility related to a chronic disease. "Other IL-6 family cytokines, including oncostatin M (OSM) and leukemia inhibitory factor (LIF), also contribute to cachexia through STAT3 activation." (PMID 40704145, 2025).
cardiac hypertrophy (2 papers, 2020 to 2023). "In summary, the present study shows for the first time that OSMR deficiency exerts adverse effects on the development of pressure overload-induced cardiac hypertrophy, which is mediated by OSM/LIFR/STAT3 signalling associated with macrophages and inflammation." (PMID 37120549, 2023). "Oncostatin M (OSM) is an inflammatory cytokine that induces cardiac hypertrophy and cardiomyocyte survival." (PMID 32825069, 2020). "Based on the in vivo and in vitro data, we concluded that OSMR deficiency could contribute to the development of pressure overload-induced cardiac hypertrophy by modulating macrophage function and the OSM/LIFR/STAT3 signalling pathway." (PMID 37120549, 2023). "We thus asked whether OSM/LIFR/STAT3 signalling was activated in macrophages and whether it participated in OSMR deletion-regulated cardiac hypertrophy." (PMID 37120549, 2023).
cervical carcinoma (2 papers, 2019 to 2022). A carcinoma arising from either the exocervical squamous epithelium or the endocervical glandular epithelium. "Therefore, our results suggest that the OSM–OSMR axis serves as an important cell-to-cell communication network in cervical cancer." (PMID 36551576, 2022). "Oncostatin M (OSM), a pleiotropic cytokine, induces STAT3 activation, exacerbating cervical cancer." (PMID 36551576, 2022). "Other studies have linked the OSM receptor to poor prognosis and reduced patient survival is in cervical carcinoma but not to the soluble OSM cytokine." (PMID 31007849, 2019).
co-infection (2 papers, 2017 to 2020). "One of the mechanisms for other viral co-infection to trigger KSHV reactivation is the secretion of inflammatory cytokines, such as oncostatin M (OSM), hepatocyte growth factor (HGF), interferon-γ (IFN-γ), and Toll-like receptors 7 and 8 (TLR7/8) triggered by co-infected viruses." (PMID 28473805, 2017).
Infertility (2 papers, 2007 to 2025). "MR results revealed genetic correlations between abnormal ADA, artemin, OSM, caspase 8, CXCL5, interleukin‐18, and LIFR levels and infertility." (PMID 40525280, 2025). "Over-expression of OSM in transgenic mice, on the other hand, leads to developmental abnormalities and infertility due to the absence of developing spermatocytes." (PMID 17996055, 2007).
intrahepatic cholangiocarcinoma (2 papers, 2024). A carcinoma that arises from the intrahepatic bile duct epithelium in any site of the intrahepatic biliary tree. "In the context of intrahepatic cholangiocarcinoma (ICC), tumor-associated neutrophils (TANs) exhibited a pro-tumorigenic character by producing elevated levels of oncostatin M, activating STAT3 signaling in ICC cells." (PMID 38474175, 2024). "In terms of mechanism, OSM (oncostatin M), which is preferentially expressed by TANs, and IL-11, which is preferentially expressed by TAMs, jointly activate STAT3 signaling in ICC (intrahepatic cholangiocarcinoma) cells, thus achieving the tumor promoting effect." (PMID 38279145, 2024).
ischemic stroke (2 papers, 2016 to 2021). A stroke disorder caused by obstruction of blood flow to the brain, due to thrombotic (local blood clot formation) or embolic (due to a blood clot or other material traveling from another site) event. "The cytokine oncostatin M may have inflammatory characteristics but has recently been shown to exhibit neuroprotective effects after ischemic stroke." (PMID 34360613, 2021).
keloid (2 papers, 2019 to 2022). An irregularly shaped, elevated mark on the skin caused by deposits of excessive amounts of collagen during wound healing. "In this context, and since OSM was overexpressed in HS but not in KS, we speculated whether OSM could protect against a chronic fibrosis mechanism that occurs in keloid scars." (PMID 30765798, 2019).
lupus nephritis (2 papers, 2017 to 2019). Glomerulonephritis in the context of systemic lupus erythematosus. "The purpose of this study was to investigate the role of oncostatin M (OSM) in tubulointerstitial lesion (TIL) in lupus nephritis (LN)." (PMID 28626343, 2017).
myeloma (2 papers, 2011 to 2023). "The myeloma cell growth activity of IL–10 is mediated through a gp130 cytokine, oncostatin M (OSM) that is frequently produced by myeloma cells." (PMID 22567049, 2011).
non-small cell lung carcinoma (2 papers, 2005 to 2025). A group of at least three distinct histological types of lung cancer, including non-small cell squamous cell carcinoma, adenocarcinoma, and large cell carcinoma. "Our analysis was consistent with similar analysis completed in human non-small cell lung cancer in which PLAU, PLAUR, IL1R2, CD274, OSM, and CXCL8 were reported to be significantly enriched in TANs relative to circulating neutrophils." (PMID 39932553, 2025). "Therefore, as first step, we determined if responsiveness to members of the IL-6 family (IL-6, OSM and LIF) were detectable in established lines of malignant human non-small cell lung carcinoma cells." (PMID 16271139, 2005).
oral squamous cell carcinoma (2 papers, 2020 to 2022). "Previous bioinformatic analysis has shown that oncostatin M (OSM) signaling is abnormally expressed in oral squamous cell carcinoma." (PMID 33224866, 2020). "It has been previously reported that OSM and its related cytokine LIF stimulate actomyosin contractility and matrix remodeling by oral squamous cell carcinoma–derived CAFs." (PMID 35192545, 2022).
skin cancer (2 papers, 2023). "Within the highly proliferative neighborhood, we find that TREM2+ skin cancer-associated macrophages (SCAMs) support the proliferation of a distinct tumor epithelial population through an immunosuppression-independent manner via oncostatin-M/JAK-STAT3 signaling." (PMID 37164949, 2023). "OSM has also been shown to be highly expressed in keratoacanthoma; originally believed to be a benign form of skin cancer, but rare cases act in a similar form to skin SCC have been reported." (PMID 37841259, 2023). "While OSM has not been extensively analyzed in all varieties of skin cancer, OSM has been shown to promote normal keratinocyte proliferation, migration, skin inflammation, and epidermal hyperplasia both in vitro and in vivo." (PMID 37841259, 2023).
type 1 diabetes (2 papers, 2021 to 2022). "Noticeably, as suggested in our study, CXCL1, TLR6 and OSM have been documented to be targeted genes of DNA methylated modification in other diseases, such as schizophrenia, type 1 diabetes and Richter syndrome." (PMID 34017996, 2021).
acute endometritis (1 paper, 2026). An acute, usually bacterial infection affecting the endometrium. "Here, we demonstrate that IL-6 family cytokines, Leukemia Inhibitory Factor (LIF) and Oncostatin M (OSM), exert complementary yet distinct immunoregulatory effects that mitigate LPS-induced acute endometritis in vivo." (PMID 42256298, 2026).
allergic asthma (1 paper, 2025). A asthma with a basis in a pathological type I hypersensitivity reaction. "Moreover, a recent study implicates these increased levels of OSM in respiratory exacerbations, given that deletion of the OSM gene or treatment with an anti-OSM blocking antibody prevented bacterial-driven exacerbations in a mouse model of allergic asthma." (PMID 40343765, 2025).
alopecia (1 paper, 2022). Hair loss usually from the scalp. "OSM, belonging to IL-6 family, negatively regulates hair growth and increased expression of OSM might contribute to alopecia." (PMID 35413801, 2022). "OSM (oncostatin M) and IL6R (interleukin 6 receptor) were significantly up-regulated in giant pandas with alopecia." (PMID 35413801, 2022).
anaphylaxis (1 paper, 2022). An acute hypersensitivity reaction that occurs from exposure to an allergen. "Genetic variations at the IL-18 locus (IL18R1 and IL18RAP) were associated with exercise-induced anaphylaxis, while MMP9 and OSM provide evidence for the involvement of innate immune pathways." (PMID 36569939, 2022).
aneurysm (1 paper, 2025). Bulging or ballooning in an area of an artery secondary to arterial wall weakening. "Hypomethylation of several genes, including CXCR4, OSM, GSTA4, MAP3K10, ADAMTS, PTBP1, and PNPLA6,61, –63,65,67,71 has been identified as being associated with the aneurysm formation." (PMID 41342741, 2025).
Atrophy (1 paper, 2020). Any weakening or degeneration, especially through lack of use. "In this context, it might also be perceived that several immune relevant factors, among them leukemia inhibitory factor (LIF) and oncostatin M (OSM), both belonging to the IL-6 cytokine family, increase with age and seem to change the intrathymic microarchitecture leading to thymic atrophy." (PMID 33233845, 2020).
autoimmune myocarditis (1 paper, 2025). Autoimmune myocarditis is an autoimmune disease that affects the heart. "Rapamycin preserves cardiac function in autoimmune myocarditis by reprogramming Cxcl9+ macrophages via the mTORC1–C/EBPβ–OSM axis." (PMID 41412038, 2025). "The mTORC1–C/EBPβ–OSM axis thus defines a critical immune–metabolic pathway sustaining myocardial inflammation and represents a tractable therapeutic target for preventing the progression of autoimmune myocarditis to chronic inflammatory cardiomyopathy." (PMID 41412038, 2025).
basal cell carcinoma (1 paper, 2024). A carcinoma involving the basal cells. "TREM1 myeloid-derived cytokines IL1 and OSM induce basal-to-inflammatory transition in vitro and in vivo through NF-κB, lowering sensitivity of patient basal cell carcinoma explant tumors to Smoothened inhibitor treatment." (PMID 39289380, 2024).
Bell's palsy (1 paper, 2025). Partial or complete paralysis of the facial muscles of one side of a person's face. "MR analysis in the present study further confirmed the causal role of OSM in the pathogenesis of Bell’s palsy, suggesting that its aberrant expression may influence the disease process by promoting neuroinflammation." (PMID 40299566, 2025). "(Genetic correlation between CCL19 and Bell’s palsy: 0.2105, p = 0.042; genetic correlation between VCAM1 and Bell’s palsy: 0.2478, p = 0.017; genetic correlation between OSM and Bell’s palsy: 0.41934, p = 0.021)." (PMID 40299566, 2025). "Checking the related studies of other proteins, we found that IL-27RA, OSM and JAK/STAT signaling pathways may play a key role in the development of Bell’s palsy." (PMID 40299566, 2025).